BCL2 (BCL2 apoptosis regulator)
Diseases named in the same sentence as BCL2 in open-access papers (continued):
Sharing a sentence is not in itself a finding about the gene and the disease.
tumor (continued). "Erbitux has been known to increase apoptosis in various tumor models by different mechanisms, including upregulation of pro-apoptotic Bax protein, decrease in the expression of anti-apoptotic molecule Bcl-2 and the activation of pro-apoptotic caspases." (PMID 19878607, 2009). "P75NTR expression in tumor cells induces a dose-dependent increase of the pro-apoptotic members (Bad, Bax and Bak) and a decrease of the anti-apoptotic members (Bcl-2 and Bcl-XL) of the Bcl-2 family." (PMID 19291307, 2009). "While Bcl-2 staining remained cytoplasmic, both percent and intensity of epithelial and stromal Bcl-2 staining decreased with tumor progression." (PMID 19852858, 2009). "In the cancerous sections, extent of Bcl-2 epithelial staining tended to decrease with increased tumor grade." (PMID 19852858, 2009). "The antiapoptotic Bcl-2 and Bcl-xL proteins and survivin, a prosurvival inhibitor of apoptosis, are major players in tumor growth and resistance to cytotoxic insults." (PMID 19270784, 2009). "Exposure to reg4 antibody resulted in a significant decrease in intra-tumor levels of pAkt, Bcl-xL, Bcl-2, survivin and cyclin D1." (PMID 19834624, 2009). "They did not compare these levels to Bcl-2 expression in normal ovarian tissue, but they did conclude that Bcl-2 expression was inversely related to tumor aggressiveness." (PMID 19852858, 2009). "Patients with low bcl-2-expressing tumours achieved a pCR 9.4 (1.17 to 75.18) times more often than those who had tumours with normal bcl-2 levels." (PMID 18380893, 2008). "In support of this view, culture supernatants from activated Kupffer cells in a mouse tumor model were able to change the balance between Bax and Bcl-2 in favor of Bax." (PMID 19079544, 2008). "Another significant finding in this study was that FVIIa and tumor-expressed TF interaction induced Bcl-2 expression, an anti-apoptotic protein regulated by the JAK/STAT5 signaling pathway." (PMID 18325115, 2008). "Numerous studies in both humans and mice have shown paradoxical effects of Bcl-2 on tumor formation." (PMID 18382684, 2008). "Overexpression of Bcl-2, Bcl-xL, and survivin in several cancers overcomes severe tumor environments and facilitates cancer progression, chemotherapeutic resistance and higher rate of recurrence." (PMID 18939995, 2008). "Nonetheless, the results indicate that p27 plays a critical role in tissue homeostasis and in tumor development in the context of Bcl-2 expression." (PMID 18382684, 2008). "miR-16 is considered a tumor suppressor, which acts by targeting BCL-2, and repressed expression is consistent with tumorigenesis." (PMID 18430245, 2008). "The Upregulation of Bax and downregulation of Bcl-2 favour the proapoptotic response over the antiapoptotic one in tumour cells, leading to the release of cytochrome c and promotion of cell death." (PMID 18854835, 2008). "In many of these studies, the tumor-suppressive effect of Bcl-2 correlated with decreased cellular proliferation." (PMID 18382684, 2008). "Bcl-2-negative tumours experienced a partial or complete tumour regression more often than Bcl-2-positive cases." (PMID 18182986, 2008). "Compared with IR-treated only CD133+, the tumorigenic properties of migration/invasion and tumor colony formation were significantly inhibited in CD133+ treated with DBH alone or DBH combined with BCL-2 siRNA." (PMID 18509505, 2008). "Necropsies of the p27 −/− Lck-Bcl-2 animals generally showed a massively enlarged thoracic tumor that in all cases appeared to arise within the thymus." (PMID 18382684, 2008). "BCL2 is one of the most widely recognized anti-apoptotic factors, whose upregulation enhances EC survival and intratumoral angiogenesis, thus promoting tumor growth." (PMID 18447899, 2008).
tumor (continued). "Nonetheless, the results indicate that p27 is a critical tumor suppressor in the context of Bcl-2 expression." (PMID 18382684, 2008). "In the present study, tumor tissues derived from curcumin treated mice showed that curcumin inhibited the exprerssion of Bcl-2 and Bcl-XL, and induced the expression of Bax and Bak." (PMID 18226269, 2008). "We then investigated the expression of ESR1/ERα and that of the five following top-ranked genes (MET, FOS, SNCG, IGFBP4, and BCL2) by RTQ-PCR on the initial set of 18 tumor samples (eight control and 10 TF)." (PMID 18928543, 2008). "Immunohistochemical staining showed the tumor cells were Thy1 positive and retained expression of human Bcl-2." (PMID 18382684, 2008). "The cloning and characterization of the Bcl-2 oncogene established the importance of apoptosis in tumor development." (PMID 17637928, 2007). "Remarkably, for the link between the primary tumour and liver metastases, apoptosis-related pathways like apoptosis-bcl2 and map kinase active transcription factor are significantly regulated." (PMID 17940512, 2007). "For example, miR-15 and miR-16 induce apoptosis by targeting Bcl2. miRNAs from the miR-17-92 cluster modulate tumor formation and function as oncogenes by influencing the translation of E2F1 mRNA." (PMID 17894887, 2007). "In rhEPO-treated animals, Bcl-2 expression was significantly lower in the tumour core compared with the tumour rim (P=0.012, Mann–Whitney U-test)." (PMID 17299396, 2007). "The quantitative evaluation of RKIP and bcl-2 expression was performed in tumour cell-enriched areas of CBCL, as determined by CD3 staining for detecting infiltrating T lymphocytes." (PMID 17473827, 2007). "BCL2 has an inhibitory effect on programmed cell death (anti-apoptotic) while BAX is a tumor suppressor that promotes apoptosis." (PMID 17868464, 2007). "The mean Bcl-2 expression was higher (2.27 ± 0.65 vs 1.01 ± 0.25 vs 6.06 ± 1.77, Control P vs Control M vs BP-4, P < 0.01) in BP-4 treated tumours when compared with the control group." (PMID 17988381, 2007). "Consistent with the cellular physiology of Bcl-2 inhibition, target tumour cells were predominantly induced to undergo apoptosis by combined treatment with immune effector cells and a Bcl-2 inhibitor." (PMID 17311012, 2007). "BAX or Bcl-2 was correlated with a higher degree of differentiation or left-sided tumours (P=0.01 or P=0.03, respectively); MSI was correlated with right-sided tumours (P<0.0001)." (PMID 17426704, 2007). "Treating TRAF2DN/Bcl-2 mice with overt disease with liposomes containing either CDDO or CDDO-Im showed that both triterpenoids were capable of reducing tumor burden in these mice." (PMID 17593960, 2007). "In contrast to control animals, Bcl-2 expression in rhEPO-treated animals was significantly different between tumour rim and core, suggesting an increased efficacy of RT in the central region of the tumour by administration of rhEPO." (PMID 17299396, 2007). "Only a few studies, however, have investigated the relationship between Bcl-2 and p27 protein expressions in tumor specimens, while there have been many studies on the prognostic value of either Bcl-2 or p27 protein expression in various cancers." (PMID 16839413, 2006).
tumor (continued). "Immunohistochemistry revealed strong expression of CD34, CD99, BCL2 and vimentin in virtually all tumour cells." (PMID 17118185, 2006). "Ki67, Mcm-2, a-Casp3, and Bcl-2 scores in the near (<1 mm from tumor) and far (>5 mm from tumor) areas of the normal and HGPIN compartments." (PMID 16545117, 2006). "The strong expression of CD99 and BCL2 in the tumour cells further supports the diagnosis of SFT, but as stand-alones these markers would not be sufficient." (PMID 17118185, 2006). "During the initial proliferative process, Bcl-2-positive tumour cells have both antiapoptotic and antiproliferative activity." (PMID 17031406, 2006). "To investigate the effects of combined treatment with AS Bcl-2 and various anticancer agents in vivo, we examined tumor growth after combined treatment of BT-474 and ZR-75-1 cells transplanted into athymic mice with AS Bcl-2 and MMC, DOX, TXL, and TXT." (PMID 16280040, 2005). "The relevance of the Bcl-2 apoptotic regulators as determinants for tumour progression and radiotherapy response in human tumours is unclear." (PMID 15685241, 2005). "The mechanism of induction of apoptosis in tumor cells appears to be related to increased caspase-3 activity, decreased Bcl-2 expression, and increased Bax expression." (PMID 15757513, 2005). "The relevance of apoptotic modulation by Bcl-2 and related proteins in tumour development and radiation response for human tumours remains undefined." (PMID 15685241, 2005). "Maspin-expressing T16 and T18 cells had a reduced level of anti-apoptotic protein Bcl-2 but an increased level of pro-apoptotic protein Bax compared to control TC tumor cells." (PMID 15907209, 2005). "Multivariate regression analysis using treatment failure as the dependent factor and bcl-2, bcl-XL, bax, bak, survivin, tumour differentiation as covariants demonstrated that bcl-2 (P<0.001), bcl-XL (P=0.007) and bax (P=0.014) were independent variables." (PMID 15928664, 2005). "In total, 53% of radioresistant tumours expressed bcl-2 compared with 11% in the radiosensitive group (P<0.001)." (PMID 15928664, 2005). "Maspin-expressing tumor cells have a reduced level of anti-apoptotic protein Bcl-2, and an increased level of pro-apoptotic protein Bax." (PMID 15907209, 2005). "Bcl-2 is anti-apoptotic in function, whereas bax is proapoptotic and it is the interaction between the two that determines the likelihood of a tumor to undergo cytotoxic drug mediated regression." (PMID 15310398, 2004). "In the present study the clinical response in terms of reduction of tumor size and immuno-histochemical response in terms of change of bcl-2/bax ratio correlated significantly with the drug induced toxicity following NACT." (PMID 15310398, 2004).
tumor (continued). "Predictions based on tumour grade, or immunohistochemical staining for BCL-2, p27 or cyclin D1, all showed a useful measure of independence from each other." (PMID 15138474, 2004). "We have addressed the question of the role of apoptosis in tumor progression by using human Bax or Bcl-2 transfected cells and then analyzing tumoral growth in rats." (PMID 15331018, 2004). "The relative role of anti apoptotic (i.e. Bcl-2) or pro-apoptotic (e.g. Bax) proteins in tumor progression is still not completely understood." (PMID 15331018, 2004). "The change in expression of apoptotic markers (Bcl-2 and Bax proteins) brought about by various chemotherapeutic regimens is being used to identify drug resistance in the tumor cells." (PMID 15310398, 2004). "Bcl2 protein expression in 100% of the CDC tumor cells was observed in four of eleven cases (36%), while the remaining seven (64%) were negative." (PMID 15357873, 2004). "The BCL2 oncoprotein inhibits apoptosis and is overexpressed by many tumours including breast, colon, prostate and tumours of the head and neck." (PMID 12592374, 2003). "Note the low basal immunoreactive signal of Bcl-2 compared to considerable level of Bcl-XL in the tumour tissues." (PMID 12644829, 2003). "Our scoring of bcl-2 positivity is admittedly subjective, but the predictive value of bcl-2 protein expression is also found with another cut-off (10% or more positive tumour cells)." (PMID 12454767, 2002). "Patients whose tumours expressed bcl-2, even with locoregionally advanced disease, were also shown to have a high likelihood of cure with aggressive combined modality therapy." (PMID 12454767, 2002). "Normal cells in such conditions would have undergone apoptosis, but it is likely that in some of these tumours, apoptosis was inhibited by the presence of Bcl-2." (PMID 11953859, 2002). "As a first step to explore sensitivity to apoptosis in tissue samples, we assayed bcl-2 protein expression by immunostaining tumour cells with a monoclonal antibody, which is widely used and gives very consistent results in paraffin-embedded specimens." (PMID 12454767, 2002). "Our study is the first to indicate that bcl-2 positivity correlates with a better tumour response to induction chemotherapy." (PMID 12454767, 2002). "Among the remaining 127 whose tumour contained less than 10% bcl-2 positive cells, 87 (59%) were responders (P=0.02)." (PMID 12454767, 2002). "Twelve out of 12 patients (100%) expressing bcl-2 protein in at least 10% of tumour cells were responders." (PMID 12454767, 2002). "Shifting the ratio of the proapoptotic protein bax to the antiapoptotic protein bcl-2 is another mechanism by which tumour cells escape the immune system and achieve resistance against drugs entering the mitochondrial apoptotic pathway." (PMID 12177810, 2002).
tumor (continued). "The context appears very different in epithelial malignancies, where bcl-2 protein expression is usually restricted to a proportion of tumour cells." (PMID 12454767, 2002). "Immunoreactive blastema cells were found in 53%, 41% and 38% of tumours for Bcl-2, Bax and for Bcl-X S/L, respectively." (PMID 11720445, 2001). "Cytoplasmic immunostaining of bax and bcl-2 was present in 65.5% and 38%, respectively, of the tumours." (PMID 11237386, 2001). "The bcl-2 expression probably exerts a role in the longevity of tumor cells submitted to hormonal therapy." (PMID 11500787, 2001). "When all tumours were divided into either a large tumour with a longitudinal tumour length of 10 mm or more, or a small tumour with a length of less than 10 mm, the large tumour expressed more bcl-2 protein than the small tumour (P = 0.0155)." (PMID 10646898, 2000). "The proliferative capacity of the tumour was assessed using the Ki-67 labelling index (LI) while bcl-2 expression was used to assess anti-apoptotic pathways." (PMID 10780524, 2000). "In contrast, the rate of bcl-2 -positive tumours was lower (31%) in Brca1 -carcinomas than in carcinomas without Brca1 mutation (90%) (P< 10(-3))." (PMID 11044356, 2000). "Tumour cells containing immunostaining for the antiapoptotic proteins Bcl-2 and Mcl-1 were present in 31% and 58% of the cases evaluated, respectively, whereas immunopositivity for the proapoptotic proteins Bax and Bak was found in 47% and 58% of the samples." (PMID 10070896, 1999). "The mean value of the apoptotic index was 2.69%+/-1.40% in Bcl-2-negative tumours and 0.68%+/-1.00% in Bcl-2-positive tumours." (PMID 9514059, 1998). "At increasing distance from this fibrovascular stroma, intermediately differentiated tumour cells express Rb, while with more advanced differentiation, proliferation ceases and Bcl-2 immunoreactivity is lost." (PMID 9099968, 1997). "Patients with tumours expressing high levels of Bcl-2 (overall score 3-6) had a significantly better disease-free (P = 0.004) and overall (P = 0.009) survival." (PMID 8679463, 1996). "Expression of bcl-2 in colonic crypts > 5 cm from the tumours was confined to crypt bases but was more extensive and intense in normal crypts < 5 mm from cancers." (PMID 8611422, 1996).